BCL2 (BCL2 apoptosis regulator)
Diseases named in the same sentence as BCL2 in open-access papers (continued):
Sharing a sentence is not in itself a finding about the gene and the disease.
melanoma (continued). "Here, we showed that melanoma cells are protected by several BCL-2 pro-survival proteins, consistent with previous reports." (PMID 31019203, 2019). "Due to the important role of intrinsic, proapoptotic pathways in melanoma, pro- and antiapoptotic Bcl-2 proteins come into particular focus." (PMID 31083589, 2019). "Similar data were obtained for Bcl-2-overexpressing metastatic B16 melanoma cells treated with SOD2 and Bcl2 antisense oligonucleotides." (PMID 29478325, 2019). "In particular, we focused on KIT, BRAF, and BCL-2, three relevant target genes in melanoma known to bear G4-forming sequences within their promoters." (PMID 31635389, 2019). "Inducible TRAIL resistance in melanoma can be explained by (i) high levels of antiapoptotic Bcl-2 proteins, (ii) high levels of XIAP, and (iii) suppressed Bax activity." (PMID 31083589, 2019). "Bcl-2 is an anti-apoptotic gene and has been involved in many cancers such as melanoma, breast, lung, and liver carcinomas." (PMID 31684176, 2019). "While BCL2 expression was higher in melanoma, BCL2 mRNA levels (RNA-seq read number) were very low in each lineage relative to MCL1 and BCL-XL." (PMID 31727888, 2019). "The Bcl2 protein is often overexpressed in several types of cancer, for instance in breast, lung, and ovarian cancer or in malignant melanoma." (PMID 30686270, 2019). "While andrographolide enhanced the expression of Bax, caspase-3, and caspase-9, it down-regulated that of Bcl-2, leading to apoptosis in melanoma B16F-10 cells, and it promoted apoptosis in pancreatic cancer cells via inhibition of STAT3 and Akt activation." (PMID 31404237, 2019). "The pro-survival members, BCL-2, BCL-XL, BCL-W, MCL-1 and BFL-1, have all been implicated in melanoma survival and chemoresistance." (PMID 31019203, 2019). "Due to the important role of intrinsic apoptosis pathways in melanoma cells, Bcl-2 proteins appear as critical targets for melanoma therapy, and particularly efficient apoptosis induction was found for Bim and Puma." (PMID 31083589, 2019). "The results showed that VB1 induced cleavage of PARP and upregulated BAX expression, whereas BCL2 expression was downregulated after VB1 treatment in different melanoma cell lines." (PMID 30400954, 2018). "Bcl-2 forced expression in different melanoma models led to increased level of both Sema5A mRNA and protein." (PMID 30454024, 2018). "Similar to previous results in oral carcinoma and melanoma cell lines, our data also revealed that the protein expression of antiapoptotic Bcl-2 was reduced and that of proapoptotic Bax was elevated 24 and 48 h after 11-dehydrosinulariolide treatment." (PMID 30513611, 2018). "In particular, Bcl-2 overexpression in human melanoma cells increases in vitro and in vivo tumor progression-associated properties and angiogenesis and promotes a cancer stem cell phenotype." (PMID 30454024, 2018). "C-Myb protein is expressed in most of the analysed melanoma cell lines, and more importantly, Bcl-2 overexpressing A375SM-SC1 cells exhibit a higher level of c-Myb protein and mRNA when compared to control cells." (PMID 30454024, 2018). "Physodic acid stimulated apoptosis due to a reduction in Bcl2 level and stimulation of Bax expression and caspase-3 activity in A375 melanoma cells." (PMID 28887754, 2018). "There are already studies evaluating melanoma and thyroid carcinoma showing the reduction of BCL-2 and MCL-1 expression in people using propranolol." (PMID 30018638, 2018). "It has been reported that MITF regulates proliferation and apoptosis through CDK2 and BCL2 in melanoma cells." (PMID 29885053, 2018). "For example, miR-219-5p inhibits the proliferation, migration and invasion of epithelial ovarian cancer cells by targeting the Twist/Wnt/β-catenin signaling pathway and the growth and metastasis of malignant melanoma by targeting BCL-2." (PMID 30474570, 2018).
melanoma (continued). "In conclusion, these results provide strong evidence that a mitochondria-mediated intrinsic apoptosis and changes in the expression of Bax and Bcl-2 are induced by CP in A375 melanoma tumor cells." (PMID 30149677, 2018). "Overall our data provide evidences supporting the role of Sema5A in melanoma progression and the involvement of Bcl-2, miR-204 and c-Myb in regulating its expression." (PMID 30454024, 2018). "This study is the first to test the effectiveness of A-1210477 (a potent MCL-1 inhibitor) in combination with ABT-263 (the BCL-2/BCL-W/BCL-XL inhibitor) in melanoma." (PMID 30185782, 2018). "We tested the efficacy of the BH3 mimetic combination of A-1210477 (an MCL-1 inhibitor) and ABT-263 (a BCL-2/BCL-XL/BCL-W inhibitor) in killing melanoma, especially MICs." (PMID 30185782, 2018). "Consistently, the expressions of pro‐apoptotic cleaved‐caspase‐9 and Bax were increased in cisplatin‐treated melanoma cells with USP4 deficiency, whereas the expression of anti‐apoptotic Bcl‐2 was deceased." (PMID 29542252, 2018). "The authors found that capsaicin determines release of mitochondrial cytochrome c, activation of caspase-3 and cleavage of poly (ADP-ribose) polymerase and finally induces apoptosis of melanoma cells through down regulation of Bcl-2." (PMID 29258175, 2017). "Pearson's correlation test was applied to detect the relationship between miR-219-5p level and Bcl-2 level in melanoma samples." (PMID 28884131, 2017). "The upregulation of miR-219-5p inhibited melanoma growth and metastasis and strengthened melanoma cells chemosensitivity by targeting Bcl-2." (PMID 28884131, 2017). "It has been reported that CT can increase the expression levels of cleaved-caspase-3 and pro-apoptotic protein Bax while decrease Bcl-2 via the ROS-mitochondrial apoptotic pathway, and arrest the cell cycle at the G2/M phase in A375 melanoma cells." (PMID 29383168, 2017). "The downregulation of survivin or Bcl-2 by siRNA sensitizes resistant melanoma cells to TRAIL-induced apoptosis." (PMID 28993697, 2017). "As a result, miR-219-5p expression was distinctly reduced in melanoma tissues and cell lines and was negatively correlated with Bcl-2 protein level in melanoma." (PMID 28884131, 2017). "So we supposed that BCL-2 was one of the most essential members for the survival of melanoma cells, and we knocked down BCL-2 in MV3 cells." (PMID 29348830, 2017). "We found that NF-κB p65 phosphorylation and BCL2 expression were increased in melanoma cells treated with IL-1β–Fib-CM." (PMID 28450382, 2017). "While BCL-XL overexpressing clones show superimposable expression level of MCL-1 protein when compared to control clones, a reduced expression of BCL-2 protein was observed in both melanoma and glioblastoma models." (PMID 29238043, 2017). "Using Bcl2-specific 3p-siRNA against melanoma, RIG-I signaling pathway activities mediated by 3p-siRNA combined with siRNA-mediated Bcl2 abrogation to induce massive metastasized lung tumor cell apoptosis." (PMID 28386261, 2017). "This study is the first to examine the efficacy of MCL-1 and BCL-2 inhibitors in combination to induce killing of both bulk melanoma cells and MICs." (PMID 27086916, 2017). "In fact, forced BCL-XL expression does not determine a modulation of MCL-1 protein, and even downregulation of BCL-2 protein in our melanoma models." (PMID 29238043, 2017). "A direct pro-apoptotic effect of imiquimod has also been described in various skin cancer cell types, including melanoma, and involved the mitochondrial pathway of apoptosis, as suggested by Bcl-2–dependent cytosolic translocation of cytochrome c." (PMID 28797090, 2017). "Apoptotic resistance in melanoma is thought to act via Bfl-1, and likewise in glioblastoma via Bcl-2 and Bcl-xL." (PMID 27805565, 2016).
melanoma (continued). "The overexpression of Bcl-2 in various cancer cell types, including glioma, neuroblasotoma, melanoma, squamous carcinoma, breast, lung, and colorectal cancer cells, increases the migratory and invasive potentials of these cells." (PMID 26621844, 2016). "Overall, data demonstrate that Erdr1 induced murine melanoma apoptosis through the regulation of Bcl-2 and Bax." (PMID 26784177, 2016). "Multiple labs including our own have repeatedly shown that NOXA/MCL-1/BCL-2 apoptotic node is a common vulnerable spot for targeting the heterogeneous cell population of melanoma." (PMID 27829238, 2016). "It was previously reported that Bcl2 inhibition sensitized resistant melanoma cells to Apo2/TRAILl (TNF related apoptosis-inducing ligand)." (PMID 26889092, 2016). "In this study, we demonstrated that Erdr1 acts as an apoptosis-stimulating factor for melanoma via the downregulation of Bcl-2 and upregulation of Bax, ultimately leading to increased apoptosis in melanoma cells both in vitro and in vivo." (PMID 26784177, 2016). "The Bax/Bcl-2 ratio in cells can regulate the susceptibility of cells to apoptosis, CoQ0 (20 μM) treatment enhanced the Bax/Bcl-2 ratio in B16F10 melanoma cells." (PMID 26968952, 2016). "The main findings of this study are 1) Upregulation of NOXA along with inhibition of BCL-2 is a promising approach to kill the bulk of melanoma cells and the MICs." (PMID 27829238, 2016). "Overexpression of Bcl-2 in melanoma cells also increases uPA receptor expression via ERK and Sp1 under hypoxic conditions." (PMID 26621844, 2016). "The results revealed a reduction in BCL-2 protein levels in both melanoma cell lines in parallel with increasing amounts of BAX." (PMID 27399772, 2016). "Our data indicated that JB upregulated the mRNA expression of Bax and downregulated the mRNA expression of Bcl-2, and subsequently decreased mitochondrial membrane potential and increased intracellular ROS level in melanoma B16F10 cells." (PMID 27796318, 2016). "A growing body of evidence has demonstrated that sorafenib induces apoptosis in melanoma cells by activating pro-apoptotic proteins (Bad, Bak and Bax), down-regulating anti-apoptotic proteins (Bcl2, Bcl-Xl and Mcl-1) and inducing PARP cleavage." (PMID 26299806, 2015). "Overexpression of anti-apoptotic proteins including Bcl-xL and Bcl-2 was observed in many melanomas, which correlates to cancer progression." (PMID 26204252, 2015). "High levels of MAPK and/or PI3K signaling typical in melanoma increase levels of anti-apoptotic Bcl-2, Mcl-1, Bcl-XL, survivin and XIAP while suppressing expression of the potent apoptotic inducer Bim and sequestering pro-apoptotic Bmf to the cytoskeleton." (PMID 26426052, 2015). "In conditions of induced hypoxia, Bcl-2 can affect the VM formation of human melanoma by regulating the expression of VE-cadherin." (PMID 25667663, 2015). "And treating melanoma cells with a Bcl-2/Bcl-xL bispecific antisense oligonucleotide resulted in a reduction of hypoxia-induced VEGF secretion." (PMID 26074971, 2015). "Combined inhibition of NF-κB and BCL2 triggers synergistic reduction of viability and induces apoptosis in melanoma cells." (PMID 26116372, 2015). "Bcl-2 reportedly affects the VM formation of human melanoma cells by regulating VE-cadherin under an induced hypoxic condition." (PMID 25667663, 2015). "For example, downregulation of miR-15a, which is observed in several cancers including melanoma, led to an overexpression of several oncogens, such as Bcl-2, Cyclin D1, and Mcl-1." (PMID 26631117, 2015).
melanoma (continued). "ABT-737 inhibits Bcl-2; Bcl-w and Bcl-XL but melanoma cells are typically protected from the cytotoxic effects of ABT-737 by high levels of Mcl-1." (PMID 26304929, 2015). "·NO/·NO-derived species have been shown to react/nitrosates bcl2 protein, stabilizing it by inhibiting its proteasomal degradation, resulting in resistance to cisplatin in human melanoma cells." (PMID 26540186, 2015). "Our findings agree with others in that the silencing of Bcl-2 improved sensitivity to cisplatin treatment in bladder cancer cells, melanoma cells, ovarian cancer cells, non-small lung cancer cells and lung adenocarcinoma cells." (PMID 26474854, 2015). "Given the recent development of highly specific BH3 mimetics and additional small molecules targeting the pro-apoptotic BCL-2 proteins, we will continue exploring how melanoma cells can be pushed over the edge to their death." (PMID 26501069, 2015). "On the other hand, a BH-3 mimetic Bcl-xL/Bcl-2 inhibitor ABT-737, as well as siRNA-mediated knockdown of Bcl-xL or Bcl-2, enhanced the activity of VS-5584 in melanoma cells." (PMID 26204252, 2015). "Oral administration of curcumin has been reported to cause down regulation of anti-apoptotic Bcl-2 and proliferating cell nuclear antigen (PCNA) in subcutaneous melanoma tumors, possibly regulated by microRNA." (PMID 25102117, 2014). "There is abundant literature that documents elevated BCL2 expression in melanoma and its contribution to melanoma and melanocyte cell survival." (PMID 24743024, 2014). "In melanoma, altered BCL-2, BCL-XL, and MCL-1 expression are associated with malignant transformation of melanocytic cells and progression to melanoma." (PMID 24983357, 2014). "In nude mice, oblimersen (an antisense oligonucleotide against Bcl-2) decreased xenografted melanoma growth." (PMID 25101298, 2014). "In our study, the combination of melatonin and thapsigargin or tunicamycin significantly downregulated Bcl-2 and upregulated Bax in melanoma cells." (PMID 24647338, 2014). "The BH3 mimetic ABT-737 (inhibiting both Bcl2 and Bcl-xL) sensitizes human melanoma cells to apoptosis induced by selective BRAF inhibitors, but does not reverse acquired resistance in vitro." (PMID 24743024, 2014). "Withaferin A alone induces apoptosis in melanoma cells by initiating production of ROS and by down regulation of Bcl-2, while a methanolic extract of Withania somnifera has been found to inhibit metastasis in a murine melanoma model." (PMID 25102117, 2014). "This conclusion has experimental and clinical relevance as different Bcl-2 over-expressing melanomas have been observed to exhibit more aggressive behavior." (PMID 24802641, 2014). "The ability of MITF to act as a prosurvival factor in melanoma is thought to partially rely on the transcriptional regulation of target genes that include two inhibitors of apoptosis: BCL2 and ML-IAP." (PMID 23480510, 2013). "BNCT decreased proliferation, altered the ECM by decreasing collagen synthesis and induced apoptosis by regulating Bcl-2/Bax in melanoma." (PMID 23527236, 2013). "Western blot analysis demonstrated that zeaxanthin decreased the expression of antiapoptotic proteins (Bcl-2 and Bcl-xL) and increased the expression of proapoptotic proteins (Bak and Bax) in zeaxanthin-treated melanoma cells." (PMID 24223611, 2013). "Recently, Hilmi and co-workers also demonstrated that IGF-1 promotes resistance to apoptosis in melanoma cells through an increased expression of BCL2, BCL-X (L), and survivin." (PMID 23915418, 2013). "Suppression of STAT5 protein in human melanoma A375 cells significantly down-regulates Bcl-2 expression, while activation of STAT5 up-regulates Bcl-xL expression." (PMID 23693134, 2013). "Our data showing that galectin-7 reduces the motility of melanoma cells are novel and worth investigating further in the context of the ability of Bcl-2 to bind galectin-7." (PMID 23658821, 2013).
melanoma (continued). "Expression of MITF has been associated with proliferation and survival of melanoma cells via its target genes CDK2, Bcl-2, livin, c-met, and HIF1α." (PMID 23349796, 2013). "In the experiments of siRNA silencing effects, we measured the suppression of Bcl-2 expression in B16/BL6 melanoma cells after delivering siRNA targeting Bcl-2 by MEL-A-containing cationic liposomes." (PMID 24300514, 2013). "Together, these results identify antiapoptotic proteins on which specifically melanoma cells rely on and, thus, provide a basis for the development of new Bcl-2 protein-targeting therapies." (PMID 22292048, 2012). "In this study, we aimed at characterizing the relevance of antiapoptotic Bcl-2 proteins in melanoma cell lines in a systematic manner." (PMID 22292048, 2012). "The results suggested that targeting of the appropriate Bcl-2 proteins, i.e., Mcl-1 or A1, represents a strategy to specifically induce apoptosis in melanoma." (PMID 22292048, 2012). "Several studies have analyzed the levels of antiapoptotic Bcl-2 proteins in melanoma, however the results were conflicting and the relevance of Bcl-2 molecules is still unclear." (PMID 22292048, 2012). "In fibroblasts and melanoma cells, the applied siRNAs efficiently abrogated expression of the respective Bcl-2 molecule." (PMID 22292048, 2012). "Together, this study demonstrates that it is possible to efficiently induce cell death specifically in melanoma cells by targeting certain antiapoptotic Bcl-2 proteins." (PMID 22292048, 2012). "Next, the relevance of antiapoptotic Bcl-2 proteins for melanoma cell survival was assessed by silencing them utilizing RNA interference." (PMID 22292048, 2012). "In this study, we systematically investigated the relevance of antiapoptotic Bcl-2 proteins in melanoma cell lines utilizing RNA interference." (PMID 22292048, 2012). "Inhibition of Mcl-1 and A1 resulted in cell death of melanoma cell lines and targeting both antiapoptotic Bcl-2 proteins simultaneously enhanced cell death to 80% whereas non-malignant cells remained unaffected." (PMID 22292048, 2012). "The rationale for the use of G3139 is based on the relevant role of bcl-2 in melanoma cell survival and on the increased sensitivity of this tumor when it is combined with chemotherapy, as it has been observed in preclinical and clinical studies." (PMID 21798045, 2011). "The expression of the survival factor CDK2 is maintained by Mitf in melanocytes and melanoma and the BCL2 gene was found to be transcribed and upregulated by Mitf under SCF stimulation." (PMID 21887372, 2011). "Our results show that combining TMZ with anti-apoptotic Bcl-2 inhibitors is a promising method for treating melanomas, and that clinical trials with TMZ and ABT-737-like compounds are warranted." (PMID 21897876, 2011). "BCL2 is expressed in up to 90% of all melanomas and its downregulation using antisense oligonucleotides was shown to be a potent sensitizer for apoptosis in a range of cell lines." (PMID 21730974, 2011). "Previous studies have already shown that antisense silencing of Bcl-2 sabotages melanoma survival, facilitating effective melanoma chemotherapy." (PMID 21234313, 2011). "Though the role of Bcl-2 expression in melanoma remains controversial in terms of tumourigenesis initiation, the cells are sure to exploit the high levels of endogenous Bcl-2 to survive." (PMID 21234313, 2011). "In melanocytes and melanoma the survival gene BCL2 is transcribed as a consequence of c-KIT- mediated Mitf activation." (PMID 21887372, 2011). "B-cell leukemia/lymphoma 2 (BCL2) is an antiapoptotic gene and is widely expressed in human melanomas." (PMID 22046555, 2011). "Anti-sense suppression of Bcl-2 leads to decreased melanoma cell survival and increased sensitivity to chemotherapy." (PMID 21479172, 2011).